NEAT1 (nuclear paraspeckle assembly transcript 1)
Diseases named in the same sentence as NEAT1 in open-access papers (continued):
Sharing a sentence is not in itself a finding about the gene and the disease.
liver fibrosis (36 papers, 2018 to 2025). "Another lncRNA, nuclear-enriched abundant transcript 1 (NEAT1), accelerates the progression of liver fibrosis and is associated with cell proliferation, invasion, and migration in HCC." (PMID 36612019, 2022). "To further explore the pathogenic roles of NEAT1 and miR-139-5p, we used in vivo murine fibrotic models to investigate the influences of their expressional alterations on liver fibrosis." (PMID 34531378, 2021). "Our study explored the pathogenic roles of lncRNA NEAT1 and its interplay with the miR-139-5p in HSCs activation and the development of liver fibrosis." (PMID 34531378, 2021). "NEAT1 is upregulated in CCl4 caused liver fibrosis, and it accelerates liver fibrosis progression; NEAT1 knockdown in HK2 cells inhibited the renal fibrosis-related markers TGF-β1 and CTGF." (PMID 34040522, 2021). "Loss of NEAT1 exhibited a pronounced inhibitory effect on liver fibrosis both in vivo and in vitro." (PMID 38511056, 2024). "In recent years, increasing studies have shown that lncRNA NEAT1 is significantly upregulated in various organ fibrosis processes, including liver fibrosis, renal fibrosis, cardiac fibrosis, and pulmonary fibrosis." (PMID 40619276, 2025). "This study unravels a novel signaling cascade involving NEAT1, miR-122, and KLF6, providing profound insights into the molecular mechanisms underlying liver fibrosis." (PMID 38511056, 2024). "The impact of the research extended to human fibrotic liver samples, revealing a positive correlation between elevated NEAT1 levels and markers of liver fibrosis, underscoring the clinical significance of these findings." (PMID 38511056, 2024). "Since the level of this lncRNA was found to upregulate in NAFLD and liver fibrosis patients, silencing NEAT1 by shRNA or siRNA was shown to suppress liver fibrosis and inflammation probably through disrupting the binding with miR-122 and miR-506." (PMID 38665220, 2024). "The research demonstrated a significant upregulation of NEAT1 expression in mice with CCl4-induced liver fibrosis and in activated HSCs, suggesting a potential involvement of NEAT1 in liver fibrosis progression." (PMID 38511056, 2024). "The involvement of NEAT1 in liver fibrosis is evident, as it inhibits miR-139-5p, leading to the upregulation of β-catenin and subsequent promotion of SOX9 expression." (PMID 39195573, 2024). "Neat1 (lnc14746*), a positive regulator of liver fibrosis 47, was down regulated 18-fold in TCDD-exposed Kupffer cells." (PMID 36711947, 2023). "When Neat1 was knocked down using an adenovirus, the CCl4-induced liver fibrosis in these animals was reduced." (PMID 36552725, 2022). "Liver fibrosis level in rat was further elevated following the injection of NEAT1 overexpressed exosomes." (PMID 35585044, 2022). "Together, all these results indicate NEAT1 downregulation and miR-139-5p overexpression alleviate liver fibrosis in mice." (PMID 34531378, 2021). "Our study extensively investigated the mechanisms of lncRNA NEAT1 and miR-139-5p in regulating liver fibrosis progression." (PMID 34531378, 2021). "Related mechanistic studies suggest that Kruppel-like factor 6 (KLF6), as an important pro-fibrotic gene, is involved in the regulation of liver fibrosis by NEAT1, and that NEAT1 overexpression induces KLF6 mRNA and protein expression." (PMID 34899344, 2021). "The roles of NEAT1, and miR-139-5p on liver fibrosis were finally confirmed by in vivo murine fibrotic model." (PMID 34531378, 2021). "Although NEAT1 was shown to regulate liver fibrosis and HSCs activation, the specific signaling pathways mediating its roles in liver fibrosis remain poorly known." (PMID 34531378, 2021). "Significant increase in lncRNA NEAT1 expression in vitro and in vivo, as well as the inhibitory effect of its deletion on liver fibrosis were observed." (PMID 34899344, 2021). "In vivo study also suggested that lncRNA NEAT1 knockdown and miR-139-5p overexpression alleviated murine liver fibrosis." (PMID 34531378, 2021).
liver fibrosis (continued). "Collectively, our study suggested that miR-139-5p sponged by lncRNA NEAT1 regulated liver fibrosis via targeting β-catenin/SOX9/TGF-β1 Pathway." (PMID 34531378, 2021). "Reportedly, lncRNA NEAT1 affects fibrosis of organs, such as liver fibrosis and renal fibrosis; however, the functional role and specific mechanism of NEAT1 in atrial fibrosis still completely unclear." (PMID 34040522, 2021). "Collectively, these results demonstrate that LncRNA NEAT1 exacerbated liver fibrosis by suppressing the expression of miR-139-5p." (PMID 34531378, 2021). "It is also important to note that inhibition of lncRNA NEAT1 inhibits the development of liver fibrosis and ASH by elevating miR-129-5p and inhibiting SOCS2." (PMID 34899344, 2021). "In liver fibrosis, numerous lncRNAs such as MALAT1, LFAR1, H19, and NEAT1 was implicated in various inflammatory chemokine pathways including transforming growth factor β (TGF-β), activation of macrophage, and C-X-C motif chemokine ligand 5 (CXCL5)." (PMID 34938356, 2021). "Masson and Sirius Red staining demonstrated that the downregulation of NEAT1 and the overexpression of miR-139-5p attenuated liver fibrosis in vivo." (PMID 34531378, 2021). "We performed a bioinformatics analysis to identify upstream mechanisms that can regulate PEG3 during the process of liver fibrosis and discovered a targeting relationship between NEAT1 and miR-129-5p." (PMID 33574830, 2020). "NEAT1 is involved in the regulation of sorafenib resistance in hepatocellular carcinoma cells by sponging miR-335 expression and accelerates liver fibrosis progression by regulating the miR-122- KLF6 axis." (PMID 32098245, 2020). "A previous study demonstrated that opposite expression patterns of NEAT1 (upregulation) and miR-29b (downregulation) were present during CCl4-induced liver fibrosis." (PMID 32098245, 2020). "Present findings give significant new evidence that NEAT1 binds to miR-129-5p and that competitive inhibition of NEAT1 or PEG3 expression by miR-129-5p can alleviate liver fibrosis via effects on the NF-κB signaling pathway." (PMID 33574830, 2020). "Taken together, we conclude that liver fibrosis of mice can be suppressed by silencing NEAT1 through inhibiting PEG3 expression." (PMID 33574830, 2020). "This outcome indicates that the NEAT1-miR-122-KLF6 axis plays a role in liver fibrosis of mice and humans." (PMID 30931332, 2019). "Neat1 expression was also observed to be elevated in whole livers and primary HSCs derived from CCl4-treated mice compared to oil-fed controls, while adenovirus-mediated knockdown of Neat1 attenuated CCl4-induced liver fibrosis in these animals." (PMID 30134610, 2018). "lncRNA NEAT1 promotes the progression of hepatic fibrosis by regulating Kruppel-like factor 6, whereas the lnc-LFAR1, which was thought to be a liver-enriched lncRNA, accelerates hepatic fibrosis via targeted TGFβ and the Notch pathway." (PMID 29495545, 2018). "Neat1 modulates cytohesin 3 expression by sponging miR-148a-3p and miR-22-3p, offering insights into liver fibrogenesis and potential lncRNA-directed therapies for liver fibrosis." (PMID 39716252, 2024). "LncRNA NEAT1/microRNA-129-5p/SOCS2 axis regulates liver fibrosis in alcoholic steatohepatitis." (PMID 39133718, 2024). "Moreover, recent research on the lncRNA Neat1 in liver fibrosis has observed the upregulation of Neat1 in fibrotic liver tissues with the activation of hepatic stellate cells, which are central to fibrosis." (PMID 39716252, 2024). "Targeting NEAT1 and its associated miR-122-KLF6 axis may potentially offer innovative therapeutic strategies for liver fibrosis, holding promise for more effective treatments in the future." (PMID 38511056, 2024). "Moreover, the therapeutic efficacy of miR-122 in mitigating liver fibrosis is compromised by elevated NEAT1 levels, which in turn increase KLF6 expression in HSCs, ultimately resulting in HSCs activation." (PMID 39195573, 2024).
liver fibrosis (continued). "LncRNA NEAT1 also plays an important role in ALD liver fibrosis." (PMID 39533619, 2024). "Furthermore, NEAT1 played a regulatory role in hepatic fibrosis by promoting the expression of GLI3, a downstream gene of the HH fibrosis pathway, whose expression was inversely related to miR-506 expression in MASLD." (PMID 39872125, 2024). "Importantly, injection of NEAT1-depleted exosomes attenuated the CCL4-induced liver fibrosis and mitigated the AST and ALT levels as well as pro-fibrotic makers, including collagen I and α-SMA." (PMID 35585044, 2022). "Herein, our study verified that lncRNA NEAT1 could target and suppress the expression of miR-139-5p directly to promote HSCs activation and excerabate liver fibrosis via β-catenin/SOX9/TGF-β1 axis." (PMID 34531378, 2021). "Bioinformatic analysis predicted that miR-139-5p was a potential target of the lncRNA NEAT1, which might promote liver fibrosis essentially." (PMID 34531378, 2021). "lncRNA NEAT1 and miR-122 interacted directly in that lncRNA NEAT1 could regulate KLF6 expression in liver fibrosis by competitively binding to miR-122, thereby accelerating HSC activation and increased cell proliferation and collagen activation." (PMID 34899344, 2021). "LncRNA NEAT1 exacerbated liver fibrosis by suppressing the expression of miR-139-5p." (PMID 34531378, 2021). "Next, we investigated the role of NEAT1 in the process of liver fibrosis." (PMID 33574830, 2020). "Furthermore, the upregulation of several lncRNAs [e.g., nuclear paraspeckle assembly transcript 1 (NEAT1), hox transcript antisense RNA (Hotair), and liver-enriched fibrosis-associated lncRNA1 (lnc-LFAR1)] has been reported to promote liver fibrosis." (PMID 32098245, 2020). "Importantly, in our study, silencing PEG3 or NEAT1 or restoring miR-129-5p tended to impede liver fibrosis in vivo and suppress activation of HSCs in vitro." (PMID 33574830, 2020). "In addition, lncRNA nuclear paraspeckle assembly transcript 1 (NEAT1) can facilitate the expression of the profibrotic gene in liver fibrosis." (PMID 31998431, 2020). "The promoted miR-129-5p and inhibited NEAT1 could improve the liver function and repress blood lipid, inflammation reaction, hepatocyte apoptosis and liver fibrosis in ethanol-induced ASH mice." (PMID 33228663, 2020). "We have found that the inhibited NEAT1 could suppress liver fibrosis in ASH mice by promoting miR-129-5p and restraining SOCS2, thereby decelerating the development of ASH." (PMID 33228663, 2020). "Knockdown of NEAT1 inhibits liver fibrosis in vivo and in vitro." (PMID 30931332, 2019). "Therefore, lncRNA NEAT1 may be a potential biomarker for liver fibrosis and further studies are needed to explore the specific mechanism of NEAT1 in the pathogenesis of liver fibrosis." (PMID 34531378, 2021). "Thus, the NEAT1/miR-29b/Atg9a regulatory axis may offer a new understanding of the pathology and treatment of liver fibrosis." (PMID 32098245, 2020). "Conversely, NEAT1 overexpression stimulated HSC activation and increased αSMA and COL1A1 levels, indicating the involvement of NEAT1 in HSC activation and liver fibrosis." (PMID 39872125, 2024). "Knockdown of NEAT1 in primary HSCs inhibited cell proliferation by 54% and suppressed expression of fibrogenic molecules, αSMA and COL1A1, resulting in improvement of liver fibrosis." (PMID 39872125, 2024). "Additionally, NEAT1 upregulates ATG9A, contributing to IGFBPrP1-induced autophagy and activation in hepatic stellate cells during liver fibrosis." (PMID 39715205, 2024). "Herein, we uncovered a new NEAT1/miR-139-5p axis promoting HSCs activation and driving liver fibrosis development by modulating the β-catenin/SOX9/TGF-β1 signaling, providing potential targets for the early diagnosis and treatment of liver fibrosis." (PMID 34531378, 2021).
liver fibrosis (continued). "This study was designed to elucidate the role of the NEAT1/miR-129-5p/SOCS2 axis in the progression of ASH, and we inferred that the inhibited NEAT1 may repress liver fibrosis in ASH mice by regulating miR-129-5p and SOCS2." (PMID 33228663, 2020). "Moreover, in human fibrotic liver samples, liver fibrosis and HSC activation show a positive correlation with NEAT1 expression." (PMID 33574830, 2020). "Our research aimed to assess the role of the NEAT1/miR-129-5p/SOCS2 axis in ASH development, and we have discovered that the inhibited NEAT1 could repress liver fibrosis and development of ASH through the elevation of miR-129-5p and suppression of SOCS2." (PMID 33228663, 2020). "Additionally, we have evidenced that the suppressed NEAT1 and SOCS2, and the promoted miR-129-5p were able to attenuate the liver fibrosis in ASH mice." (PMID 33228663, 2020). "It was also reported that NEAT1 could affect HCC through interaction with microRNA-129-5p (miR-129-5p), which has also been proposed as a biomarker of liver fibrosis responsible for the activation of hepatic stellate cells (HSCs) and collagen synthesis." (PMID 33574830, 2020). "In addition, a significant increase in NEAT1 expression was found in activated mouse hepatic stellate cells (HSC) and carbon tetrachloride- (CCl4-) induced mouse liver fibrosis models." (PMID 30931332, 2019).
multiple myeloma (35 papers, 2017 to 2026). "Further more we supposed that if the expression of lncRNA NEAT1 may associated with Dex resistant in clinic, and it may be and predict the prognosis and treatment efficacy of multiple myeloma." (PMID 37407915, 2023). "Moreover, the overexpression of NEAT1 also caused multiple myeloma cells to proliferate, migrate, and invade; however, resveratrol suppressed this effect." (PMID 35566016, 2022). "The lncRNA NEAT1 is overexpressed in multiple myeloma (MM) plasma cells and plays a key role in MM pathogenesis." (PMID 41928426, 2026). "Exosomal NEAT1 from myeloma cells modulates EZH2/PBX1, impairing NK-cell function and promoting immune evasion." (PMID 40410719, 2025). "Knockdown of PBX1 attenuates the effect of NEAT1-silenced exosomes on NK cells and multiple myeloma cells." (PMID 39346921, 2024). "PCAT1, ANRIL, H19, ANGPTL1‐3, or NEAT1 upregulation induced myeloma cells insensitive to bortezomib, whereas CRNDE overexpression leads to dexamethasone tolerance." (PMID 36057947, 2023). "It was surprised that the expression level of NEAT1 was significantly higher in patients with multiple myeloma than in healthy donors." (PMID 37407915, 2023). "For example, resveratrol targets metastasis associated lung adenocarcinoma transcript 1 (Malat1) in Parkinson’s disease and noncoding nuclear-enriched abundant transcript 2 (Neat1) in myeloma." (PMID 37796408, 2023). "NEAT1-lncRNA is upregulated in multiple myeloma and it is involved in mechanisms of cellular stress response." (PMID 37486375, 2023). "We found that NEAT1 is dysregulated in the bone marrow of patients with multiple myeloma, but bone marrow puncture is an invasive procedure and inconvenient, that is awfully resisted by many patients." (PMID 37407915, 2023). "LncRNA NEAT1 was over-expressed in multiple myeloma cells exposed in nutrient-deprived environment and provoked higher aggression by inducing two fundamental kinases (ATM and DNA-PKcs) and their targets (pRPA32 and pCHK2)." (PMID 36541918, 2022). "These proteins, along with NEAT1, enable paraspeckle formation, thus promoting multiple myeloma cell survival." (PMID 35886974, 2022). "In multiple myeloma (MM) cells, where the lncRNA NEAT1 is highly expressed and induces cells proliferation, migration and invasion, resveratrol reversed the negative effect of NEAT1 through the Wnt/β-catenin signaling pathway." (PMID 35912113, 2022). "The functional axis composed of NEAT1/miR-214/B7-H3 regulates M2 polarization and accelerates the progression of multiple myeloma." (PMID 36263199, 2022). "Study reported that lncRNA nuclear-enriched abundant transcript 1(NEAT1) sponged miR-214 to target regulation B7-H3 thereby promoted M2 macrophage polarization via phosphorylating JAK2/STAT3 signaling in multiple myeloma." (PMID 36153596, 2022). "In multiple myeloma, the tumorigenic lncRNA nuclear paraspeckle assembly transcript 1 (NEAT1) induces M2 polarization and promotes cancer progression by sponging miR-214 and upregulating the expression of B7-H3, a target of miR-214." (PMID 36263199, 2022). "In multiple myeloma, lncRNA NEAT1, by targeting miR-214, upregulates B7-H3, promoting M2 macrophage polarization and tumor development." (PMID 33800752, 2021). "NEAT1 promoted the occurrence and development of multiple myeloma through the JAK2/STAT3 signaling pathway." (PMID 35011565, 2021). "In multiple myeloma cells, the lncRNA NEAT1 upregulates DNA-repair proteins and enables multiple myeloma cells to resist massive amounts of genotoxic stress." (PMID 32266130, 2020). "Recently, NEAT1 has been proven to be highly expressed in multiple myeloma, and knockdown of NEAT1 inhibited the invasion and metastasis of myeloma cells." (PMID 33267910, 2020). "NEAT1 is overexpressed in most cancer types, except leukemia and myeloma, where it is down-regulated." (PMID 32591022, 2020).